RN7SKP45 (RN7SK pseudogene 45)
Gene: Miscellaneous RNA gene on chromosome 3 (56,072,104 to 56,072,407, forward strand). Ensembl gene ENSG00000200379.
Homologues: Orthologues: chimpanzee 7SK (98% identical), guinea pig 7SK (65% identical). Paralogues in human: RN7SKP180 (78% identical), RN7SKP243 (77% identical), RN7SKP9 (77% identical), 7SK (76% identical), RN7SKP37 (76% identical), RN7SKP78 (75% identical), RN7SKP79 (75% identical), RN7SKP203 (75% identical), RN7SKP211 (75% identical), RN7SKP90 (75% identical), RN7SKP133 (74% identical), RN7SKP250 (74% identical), and 283 more.